CCL24 (C-C motif chemokine ligand 24)
Description:
Chemotactic for resting T-lymphocytes, and eosinophils. Has lower chemotactic activity for neutrophils but none for monocytes and activated lymphocytes. Is a strong suppressor of colony formation by a multipotential hematopoietic progenitor cell line. Binds to CCR3.
Synonyms: Eotaxin-2; MPIF-2; MPIF2; SCYA24; Ckb-6
Tractability: Antibody: UniProt places it where antibodies can reach, with high confidence; UniProt predicts a signal peptide or a membrane-spanning region; its Gene Ontology location is reachable by antibodies, with medium confidence.
Gene: Protein-coding gene on chromosome 7 (75,810,825 to 75,823,943, reverse strand). Ensembl gene ENSG00000106178.
Subcellular location: Secreted
Gene Ontology:
Molecular function: CCR3 chemokine receptor binding; chemokine activity; protein binding; receptor ligand activity; CCR chemokine receptor binding; cytokine activity
Biological process: chemokine-mediated signaling pathway; cytoskeleton organization; eosinophil chemotaxis; positive regulation of actin filament polymerization; positive regulation of cell migration; positive regulation of endothelial cell proliferation; regulation of cell shape; antimicrobial humoral immune response mediated by antimicrobial peptide; cell chemotaxis; cell-cell signaling; chemotaxis; immune response; inflammatory response; signal transduction; positive regulation of angiogenesis; positive regulation of inflammatory response
Cellular component: extracellular region
Genetic constraint (gnomAD): Loss-of-function variants: 5 observed, 9.16 expected, observed/expected ratio (o/e) 0.55, 90% interval 0.28 to 1.15. That is too few expected variants to judge how well the gene tolerates losing a copy. Missense variants: 120 observed, 144.31 expected, observed/expected ratio (o/e) 0.83, 90% interval 0.72 to 0.97. Synonymous variants: 55 observed, 53.36 expected, observed/expected ratio (o/e) 1.03, 90% interval 0.83 to 1.29.
Homologues: Orthologues: chimpanzee CCL24 (97% identical), pig CCL24 (61% identical), dog CCL24 (61% identical), mouse Ccl24 (58% identical), zebrafish ccl35.1 (21% identical), zebrafish ccl35.2 (21% identical). Paralogues in human: CCL13 (29% identical), CCL21 (29% identical), CCL7 (29% identical), CCL11 (28% identical), CCL3L3 (28% identical), CCL26 (27% identical), CCL3 (27% identical), CCL8 (27% identical), CCL1 (26% identical), CCL15 (26% identical), CCL18 (26% identical), CCL2 (26% identical), and 14 more.
Diseases named in the same sentence as CCL24 in open-access papers:
CCL24 is named in the same sentence as 150 diseases in open-access papers, as found by Europe PMC text mining. Sharing a sentence is not in itself a finding about the gene and the disease. The quoted sentences say what the papers report.
asthma (49 papers, 2007 to 2026). "Our findings reveal that iNOS can be a risk factor of comorbidity of PAR and asthma and decreasing lung function, evidenced by its correlation with CCL-24." (PMID 38167134, 2024). "In addition, polymorphisms in the CCL24 gene have been associated with the development of asthma." (PMID 27484038, 2017). "Proteomic analysis revealed 179 differentially expressed proteins (DEPs), with a notable finding that CCL24, a key eosinophil-recruiting chemokine, was completely suppressed in Niudali-treated mice but highly expressed in the asthma model." (PMID 42318010, 2026). "Using genetically engineered mice, it was demonstrated that CCL24 had a dominant role in the recruitment of eosinophils into the airways of mice in an asthma model." (PMID 32687504, 2020). "By interacting with CCR3, CCL24 (C-C motif chemokine ligand 24, also known as eotaxin-2) is an important mediator in Th2 cell-mediated allergic inflammation occurring in asthma, allergic rhinitis, and atopic dermatitis." (PMID 32826979, 2020). "More importantly, 11 mRNAs were overlapped in our sequencing data, MalaCards database and asthma-associated genes, including IL4, IL-10, MMP9, VCAM-1, Il1rl1, Alox5, Il1rn, Ccr3, Cysltr1, Epx, and Ccl24." (PMID 31231429, 2019). "On univariate analysis, allergic rhinitis in sibling, paternal allergic rhinitis, high expression of eosinophils count, IL-1β and CCL-24, history of active asthma and atopy correlated with severity of AR." (PMID 31548841, 2019). "Some highly significant genes in the microarray analysis also relevant to asthma (Ccl2, Ccl11, Ccl24 and Cxcl5) were further confirmed by quantitative PCR." (PMID 25318534, 2014). "Among the up-regulated genes were 3 associated with inhibition of proliferation (Gpnmb, Setd8, Runx2) and 1 promoting inflammatory and immune responses (Pik3cd), as well as 4 asthma-related genes (Arg1, Ccl24, Slc7a2, Mcpt1) identifiable only through qRT-PCR." (PMID 18087596, 2007). "The qRT-PCR analysis of these samples verified results for Ccl8 and indicated a down-regulation of 10 other asthma-related genes (Arg1, Ccl11, Ccl24, Ear11, Mcpt1, Sprr2a, Chi3l3, Chi3l4, Chia, Slc7a2) in EOO versus AOO mice." (PMID 18087596, 2007). "CCL2, which we detected in BAL, is a chemoattractant for monocytes and basophils while CCL24, also known as eotaxin-2, recruits eosinophils and basophils, is elevated in some forms of asthma and functions to induce inflammation after bronchial allergen challenge." (PMID 40725026, 2025). "Furthermore, expression of genes whose expression correlates with asthma, including Il9, Il4, Il13, Ccl11, Ccl24, and Muc5ac, was much lower in recipients of Id1 cKO Th9 cells." (PMID 37867222, 2023). "Moreover, miR-221 was described to correlate with airway eosinophilia in asthma and further increased CCL-24, CCL-26, and POSTN in asthmatic airways." (PMID 36172292, 2022). "Systemic treatment with JWH133 intensified the eotaxin-2/CCL24-induced eosinophil recruitment into the airways of IL-5Tg mice and aggravated ovalbumin-induced asthma by enhancing eosinophil migration into the lungs and deteriorating airway hyperreactivity in a CB2-dependent manner." (PMID 34393784, 2021). "CCL24, also known as eotaxin‐2, is a C‐C motif‐containing chemokine that facilitates eosinophil recruitment to sites of inflammatory responses to parasitic infections, as well as in allergic and autoimmune diseases, such as asthma and atopic dermatitis." (PMID 32419252, 2020). "In the present study, we also investigated the chemokine ligand levels, that is, CCL11 (also known as eotaxin), and CCL24 (also known as eotaxin-2 or myeloid progenitor inhibitor factor-2), which are all epithelial cell–derived chemokines involved in the pathogenesis of asthma and rhinitis." (PMID 31548841, 2019). "It is known that CCL5, CCL11, and CCL24 may contribute to the airway recruitment of fibrocytes in severe asthma." (PMID 31548841, 2019).
asthma (continued). "Compared to early-onset Th2 asthma, adult-onset asthma is characterized by the presence of raised eotaxine-2/CCL24 levels; eotaxine-2/CCL24 is a potent proeosinophilic chemokine, which might be the cause of the raised eosinophil count." (PMID 28503545, 2017). "However, when examined by qRT-PCR, four asthma-related genes were identified as up-regulated (Arg1, Ccl24, Slc7a2, Mcpt1)." (PMID 18087596, 2007). "However, the few asthma/inflammatory genes that are differentially expressed (Pik3cd, Arg1, Slc7a2, Ccl24, Mcpt1) are all up-regulated in ETS-exposed mice." (PMID 18087596, 2007). "In addition, Ccl11, Ccl24, and Muc5ac, which correlate with asthma, decreased in Id1 cKO mice." (PMID 37867222, 2023). "Four genes linked to asthma or lung inflammation (Arg1, Ccl24, Slc7a2, Mcpt1) that did not pass all the microarray filtering criteria were confirmed by qRT-PCR as being up-regulated in ESO versus ASO mice, which is consistent with an enhanced lung response in ETS-exposed mice." (PMID 18087596, 2007). "Recently, it was demonstrated that mainly IL-13 induces CCL11 and CCL24 in fibroblasts and monocytes, which was required for eosinophil attraction in HDM-induced murine asthma." (PMID 40276331, 2025). "However, it is important to note that some diseases, suchas asthma, are associated with increased plasma levels of CCL24, which reinforcesthe view that this chemokine is not specific for silicosis but rather may functionas an inflammatory marker." (PMID 39606764, 2024). "IL-1β, CCL24, and iNOS were significantly higher and E-cadherin was lower in the PAR and asthma group." (PMID 38167134, 2024). "CCL24 was expressed by cytokeratin+ epithelial cells, CD31+ endothelial cells, and CD68+ macrophages, especially in asthma, CCL24 facilitated eosinophil migrating into lungs by upregulating adhesion ability to endothelial cells." (PMID 28042950, 2017). "It is well known that eosinophils that respond to a variety of CC chemokines, such as CCL11 (eotaxin), CCL24 (eotaxin-2) and CCL26 (eotaxin-3), are proinflammatory granulocytes with significant roles in several inflammatory diseases, including asthma." (PMID 27304950, 2016). "Since MO-DCs may present allergens to Th-2 lymphocytes, promote T cell stimulation via the OX40 ligand, and produce proinflammatory chemokines such as CCL2 and CCL24 (eotaxin 2), the role of FUT2 in MO-DC accumulation is significant in asthma." (PMID 38785919, 2024). "Eotaxins are increased in the airways of subjects with asthma, and we have previously shown that neutralizing antibodies against eotaxin-1/CCL11 and eotxin-2/CCL24 reduces the number of infiltrating eosinophils in the BALF of OVA-sensitized and challenged mice." (PMID 33946872, 2021). "In terms of differences in the expression of biomarkers between patients with AR and asthma and patients with AR alone, we found that in the group with asthma, expression of CCL-24 were significantly higher than in the group without asthma (p = 0.006)." (PMID 31548841, 2019). "And the expression of IL-1β and CCL-24 in patients with activation of asthma (N = 9) in 1 year was significantly higher than in children without activation of asthma (p < 0.001 and p = 0.004)." (PMID 31548841, 2019). "It will be important to determine whether TPL-2 also regulates CCL24 in human DCs and whether the TPL-2 pathway is compromised in those with severe asthma." (PMID 27484038, 2017). "In support of this, sputum from patients with severe, treatment-refractory asthma had elevated levels of Ccl24, compared with the sputum of those with nonsevere asthma." (PMID 27484038, 2017). "Further study is required to determine whether TPL-2 regulates chemokine secretion, including Ccl24, in human cells and whether alterations in TPL-2 expression/signaling contribute to severe asthma." (PMID 27484038, 2017).
asthma (continued). "Similarly, elevated expression of tissue Ccl24 has been observed in those with severe asthma, correlating with sputum eosinophilia, lower FEV1, and more asthma exacerbations." (PMID 27484038, 2017). "In asthma (particularly T2-high severe asthma), eosinophils are actively recruited to airway tissues in response to chemokines upregulated by IL-4 and IL-13 such as eotaxin-1 (CCL11), eotaxin-2 (CCL24), and eotaxin-3 (CCL26), which binds to CCR3 receptors on eosinophils." (PMID 40004192, 2025). "A recent study showed that IL-35 can reduce airway eosinophilia through the inhibition of eosinophil-attracting chemokines (CCL24 and CCL11) and concluded that IL-35 could be a treatment option for reducing the recruitment of eosinophils into tissues in disorders such as asthma." (PMID 39597537, 2024). "Rapamycin treatment of established asthma, however, increased mRNA levels of CCL11 and did not affect the expression of CCL7 or CCL24." (PMID 22685525, 2012).
eosinophilia (28 papers, 2013 to 2026). "In support of this observation, Ccl24-deficient mice are capable of mounting low levels of airway eosinophilia after ovalbumin challenge." (PMID 27484038, 2017). "This is true also of the association of increased CCL24 levels in the airways of RV infected Tbet deficient mice with airways eosinophilia and further work is therefore required to determine whether chemokines play a role in the Th2 and eosinophil responses observed in Tbet deficient mice." (PMID 27683080, 2016). "Particularly tissue and peripheral eosinophilia appeared to be a direct consequence of an increased secretion of CCL24 by PSCΔNEMO cells." (PMID 35624133, 2022). "PSCΔNEMO cells contribute to tissue and peripheral eosinophilia through a massive secretion of CCL24." (PMID 35624133, 2022). "Isolated PSCΔNEMO cells express high levels of several chemokines including CCL24 which contributes to tissue eosinophilia." (PMID 35624133, 2022). "BAL levels of CCL24 (eotaxin-2), a surrogate marker of eosinophilia, were significantly increased in allergic HFD lungs." (PMID 32184787, 2020). "This correlated with enhanced Ccl24 (Eotaxin-2) expression and increased eosinophilia in infected Nlrp3−/− mice." (PMID 31586037, 2019). "Specifically, blocking Ccl24 reduced airway eosinophilia and lymphocyte recruitment in the BAL fluid of mice given Map3k8−/− BMDCs, compared with isotype-treated mice." (PMID 27484038, 2017). "Consistent with this, neutralizing Ccl24 dramatically reduced airway eosinophilia, lymphocyte infiltration, and lung inflammation in allergic mice given Map3k8−/− BMDCs, highlighting a key role of Ccl24 in mediating severe airway allergy in Map3k8−/− mice." (PMID 27484038, 2017). "TPL-2 inhibited Ccl24 expression in lung DCs, and blockade of Ccl24 prevented the exaggerated airway eosinophilia and lung inflammation in mice given HDM-pulsed Map3k8−/− DCs." (PMID 27484038, 2017). "Cutaneous eosinophilia persisted in Sharpin−/−, Il4ra−/− mice, although expression of Il5 mRNA was reduced and the expression of Ccl11 and Ccl24 was completely abolished." (PMID 24465642, 2014). "In addition to increased NO levels and arginase activity, coinfected mice presented a classic Th2 anti-Sv response: eosinophilia, higher levels of alternate activated macrophages (M2), increased concentrations of CCL24 and IL-4, and lower levels of IL-1β." (PMID 37888224, 2023). "Taken together, reduced expression of CCR3 on eosinophils and CCL24/eotaxin-2 in the airways could potentially explain the decrease in airway eosinophilia observed in mice given rapamycin in addition to IL-33." (PMID 35720347, 2022). "CCL24 is likely involved in the pathogenesis of chronic nasal hypereosinophilia; nasal fluid CCL24 levels show a significant correlation with the degree of eosinophilia and clinical symptoms." (PMID 31548841, 2019). "In challenged lungs, reduced inflammation and eosinophilia were accompanied by lower levels of chemokines CCL17 and CCL24, which attract Th2 cells and eosinophils, respectively." (PMID 41074677, 2026). "Basophil depletion during sensitization reduces lung eosinophilia and CCL17/CCL24 level, while additional basophil absence during challenge is required to also impair Il4/Il13 expression." (PMID 41074677, 2026). "IL-5 promotes eosinophilia, and IL-4 and IL-13 enhance the production of eosinophil chemoattractants (CCL11/eotaxin-1, CCL24/eotaxin-2, and CCL26/eotaxin-3) and activate B cells, macrophages, fibroblasts, epithelial cells, and goblet cells." (PMID 37674852, 2023). "As expected, IL-33 induced airway and bone marrow eosinophilia and elevated CCL24/eotaxin-2 levels in BALF compared to control groups." (PMID 35720347, 2022). "OVA inhalation significantly upregulated both CCL11 and CCL24 expression in the lungs of neonatally OVA-exposed mice, compatible with the presence of BALF eosinophilia." (PMID 34207237, 2021).
eosinophilia (continued). "The expression of CCL11, CCL24, and IL33 increased significantly in mice treated with PPE alone, which may contribute to PPE-induced eosinophilia in the lung." (PMID 34950055, 2021). "Eosinophilia in lung tissue is driven partially by the recruitment of eosinophils to the lung mucosa and interstitium due to airway produced IL-5, as well as production of eotaxin (CCL11), eotaxin-2 (CCL24), and eotaxin-3 (CCL26)." (PMID 26346739, 2015). "The underlying mechanism for this effect is unclear, as the reduction in eosinophilia was not correlated with a decrease in IL-5, CCL11, or CCL24, and eosinophil migration itself was not inhibited by IL-2c." (PMID 29196657, 2017).
allergic disease (15 papers, 2008 to 2025). An immune response that occurs following re-exposure to an innocuous antigen, and that requires the presence of existing antibodies against that antigen. "C–C motif chemokine ligand 24 (CCL24, also named eotaxin-2), a type of inflammatory chemokine, has been reported to be associated with various diseases, such as primary biliary cholangitis, allergies, and eosinophilic esophagitis." (PMID 32051393, 2020). "Return to IL-4 modulating the expression of CCL24 in allergy, many study focused the relationship of Rho GTPase family and Th2 cell factors." (PMID 28042950, 2017). "Review CCL24 research in allergy, some study invariably involved Th2 cell factors IL-4 or/and IL-13." (PMID 28042950, 2017). "Eosinophils expressing the chemokine receptor CCR3 are attracted by the activation of the chemokine eotaxin family, which consists of eotaxin-1 (CCL11), eotaxin-2 (CCL24), and eotaxin-3 (CCL26), in allergic diseases." (PMID 39962262, 2025). "CCL24, known as eotaxin-2, MPIF-2, or Ckβ-6, had been studied in allergies and eosinophilic esophagitis for many years since its discovery in 1997." (PMID 28042950, 2017). "CCL24, CCL17 and CCL22 were increased in OVA immunized mice in comparison to the adjuvant immunized mice as expected in the current model for allergy." (PMID 27580126, 2016). "Eotaxins (ccl11 and ccl24) and regulated on activation normal T cell expressed and secreted (RANTES or ccl5) are potent chemoattractants that mediate eosinophil chemotaxis and allergy signaling." (PMID 30252910, 2018). "Collectively, these results suggest that eosinophils count, IL-1β and CCL-24 were overexpressed in children with moderate to severe PAR and with other active allergic diseases and therefore, can be used as a biomarker of exacerbation or activation of allergic diseases including AR." (PMID 31548841, 2019).
COVID-19 (10 papers, 2020 to 2024). A disease caused by infection with severe acute respiratory syndrome coronavirus 2. "COVID-19 patients who progressed showed persistent Th2 inflammation, which was strongly affected by CCL24." (PMID 38543303, 2024). "Many proinflammatory cytokines, including IFN-gamma and Eotaxin2/CCL24 which are elevated in our study’s group with sputum production, have been shown to be correlated with worse clinical outcomes associated with COVID-19." (PMID 39052548, 2024). "Recently, it was shown that it is possible to predict which COVID-19 patients will clinically deteriorate since they have a blunted IFN and an exaggerated CCL24 airway response." (PMID 37371071, 2023). "Network analysis of inflammatory mediators in the nasal mucosa and serum showed an anti-inflammatory response (IL-10 upregulation) and T2 inflammatory (CCL11 and CCL24 upregulation) response with co-existent inflammation (upregulation of IL-6 and CXCL8) in early COVID-19." (PMID 35397798, 2022).
nasal polyps (10 papers, 2012 to 2025). "Some investigators found that CCL24 was highly expressed in patients with nasal polyps." (PMID 40720416, 2025). "Levels of IL-4, IL-5, IL-13, and ECP and the eotaxins CCL11, CCL24, and CCL26 were elevated in the nasal polyps of patients with eCRSwNP or noeCRSwNP." (PMID 35747690, 2022). "In nasal polyps, immunoreactivity of the chemokine ligand (CCL) eotaxin subfamily comprising eotaxin-1 (CCL11), eotaxin-2 (CCL24), and eotaxin-3 (CCL26) was noted." (PMID 30778348, 2019). "Chemokines secreted by epithelial cells include eotaxin-1 (CCL11), eotaxin-2 (CCL24) and eotaxin-3 (CCL26) which have been demonstrated in increased numbers in nasal polyps as compared to healthy controls." (PMID 29376948, 2016).